EGFR (epidermal growth factor receptor)
Diseases named in the same sentence as EGFR in open-access papers (continued):
Sharing a sentence is not in itself a finding about the gene and the disease.
triple-negative breast carcinoma (continued). "However, because the majority of triple negative breast cancer is basal-like, our results suggest that combination EGFR and PARP inhibition may potentially impact a large portion of the triple negative breast cancer patient population." (PMID 23071597, 2012). "Similarly, in triple negative breast cancer, higher expression of UBASH3B promotes dephosphorylation and inactivation of CBL, which in turn loses ability to ubiquitinate and induce degradation of the epidermal growth factor receptor (EGFR), leading to accelerated cancer progression." (PMID 38461240, 2024). "Due to their lack of receptors/molecular targets, triple negative breast cancers (TNBCs) have more limited treatment options than those that express ER and PR or overexpress HER2 and EGFR, which can be used as targets for therapy." (PMID 35327957, 2022). "Unfortunately, a triple-negative breast cancer cell line, MDA-MB-231, which is known to overexpress EGFR, showed a refractory phenotype as well as no obvious change in EGFR levels in response to the co-treatment." (PMID 27494858, 2016). "Moreover, EGFR signaling is also impaired in triple negative breast cancer cells lacking STARD7, at least due to deregulated EGFR trafficking to lysosomes." (PMID 40443279, 2025). "LPAR1 and LPAR6 gene expression were highest in ER+HER2– (estrogen-receptor-positive, human-epidermal-growth-factor-receptor-negative) tumors and lowest in TNBC (triple negative breast cancer) tumors in all three cohorts, while this pattern was reversed for LPAR2 and LPAR3 (all p < 0.001)." (PMID 37372960, 2023). "It has been hypothesized that epidermal growth factor receptor and CK5/6 are positive predictive markers of the triple-negative breast cancer (TNBC) response to everolimus, although our data do not support this hypothesis." (PMID 24724101, 2014).
bladder cancer (385 papers, 1994 to 2026). "For example, METTL1 is associated with poor prognosis in bladder cancer, and it regulates the translation of EGFR/EFEMP1 by modifying certain tRNAs to inhibit the proliferation, migration and invasion of bladder cancer cells." (PMID 40443650, 2025). "EGFR overexpression and mutation are well-documented drivers of bladder cancer progression, contributing to enhanced proliferation, invasion, and epithelial–mesenchymal transition (EMT)." (PMID 41256326, 2025). "Currently, there is increasing evidence about the association between EGFR overexpression and the response to treatment in bladder cancer." (PMID 39678505, 2024). "While both EGFR inhibitors were mildly effective in interfering with the growth of T24 human bladder cancer cells, both agents caused significant autophagy activation." (PMID 39272847, 2024). "For instance, EGFR, previously associated with SEs, is a crucial factor in bladder cancer cell dedifferentiation expressed in the basal layer and associated with a less differentiated state of normal urothelial cells." (PMID 37501079, 2023). "Regarding bladder cancer, the results of previous studies have revealed that more than half of cases of bladder cancer had EGFR overexpression, which was associated with high tumour grade, stage, tumour progression, and poor prognosis." (PMID 37892022, 2023). "Other studies have shown that the EGFR 521R variant is associated with a poor prognosis in bladder cancer and colon cancer." (PMID 36347915, 2022). "Using overexpression and knockdown approaches and pharmacological inhibitors, we identify a novel molecular mechanism involving the EGFR-ProT-NF-κB-HOTAIR signaling axis in cisplatin-associated cancer cachexia in bladder cancer cells." (PMID 36471329, 2022). "SH3 domain-binding glutamic acid-rich protein-like 3 (SH3BGRL3), a thioredoxin superfamily member, shows a significant association with increased levels of EGFR in bladder cancer." (PMID 32922662, 2020). "Amplification and mutations of EGFR have been shown to be driving events in several solid tumors including bladder cancer." (PMID 31871844, 2019). "We were also able to detect the variable presence of the bladder cancer-associated gene, EGFR, using the in situ fluorescence hybridization (FISH) assay." (PMID 31480265, 2019). "Three SNPs [rs2344673 (RGS5), rs3756712 (PDCD6), and rs2293347 (EGFR)] were associated with events of bladder cancer death, albeit in different subgroups." (PMID 31681611, 2019). "Treatment of EJ28Luc bladder carcinoma cells with 213Bi-anti-EGFR-MAb caused similar effects as to induction of DNA double-stand breaks (data not shown)." (PMID 31165773, 2019). "EGFR protein overexpression in TCC/bladder cancer has been linked to TCC grade, stage, and survival outcomes." (PMID 29721181, 2018). "Epidermal growth factor receptor (EGFR) overexpression is believed to be associated with bladder cancer (BC) progression and poor clinical outcomes." (PMID 30413194, 2018). "We performed EGFR immunohistochemistry on 126 cases of bladder cancer and association of EGFR expression with tumor grade, lamina propria invasion, deep muscle invasion and recurrence of disease was evaluated." (PMID 29879970, 2018). "Our data is in accordance with the reported literature; as we found significant association of EGFR expression with tumor grade, lamina propria and muscularis propria invasion; which are among most important prognostic factors in bladder cancer." (PMID 29879970, 2018). "Based on recent comprehensive analyses of the genomic landscape of bladder cancer patients, several mutated genes have been identified as possible therapeutic targets, including epithelial growth factor receptor (EGFR) gene." (PMID 28165387, 2017). "The efficacy of gefitinib, a well-known EGFR tyrosine kinase inhibitor, combined with metformin was assessed on bladder cancer and underlying mechanisms were explored." (PMID 27334428, 2016).
bladder cancer (continued). "In this study, we aim to examine the effects of a combined treatment of metformin with gefitinib, a selective EGFR-TKI in bladder cancer and explore their mechanisms underlying." (PMID 27334428, 2016). "These allowed us to focus on interesting aspects and identify mechanisms potentially underlying the different responses of bladder cancer cells to different growth factor receptors (EGFR versus FGFR3)." (PMID 24250280, 2013). "Hereafter, we focus on the impact of the MAPK network in urinary bladder cancer, with particular emphasis on the differential behaviour between EGFR over-expression and FGFR3 activating mutation." (PMID 24250280, 2013). "A number of studies have reported the association of EGFR and ErbB2 overexpression with advanced stages of bladder cancer." (PMID 22991510, 2012). "Several studies have shown that the presence of epidermal growth factor receptor (EGFR) in bladder cancer is associated with high tumour stage and grade and is a strong independent predictor of tumour stage progression and poor long-term survival." (PMID 17311025, 2007). "Several studies have demonstrated that the presence of epidermal growth factor receptor (EGFR) in bladder cancer is associated with high tumour stage and grade, and is a strong independent predictor of tumour progression and poor long-term survival." (PMID 15083203, 2004). "The epidermal growth factor system has been associated to prognosis in patients with bladder cancer based mainly on the expression of the epidermal growth factor (EGF) receptor 1 (EGFR) and HER2 and their activating ligands." (PMID 15583696, 2004). "In bladder cancer, high expression of EGFR is closely associated with tumor progression." (PMID 40433388, 2025). "In addition to apoptosis, our enrichment analysis also highlighted the PI3K-Akt and EGFR signaling pathways as significantly associated with the predicted targets of Myristica fragrans in bladder cancer." (PMID 41256326, 2025). "EGFR is positively associated with poor outcomes in bladder cancer." (PMID 38172584, 2024). "EGFR is overexpressed in bladder cancer and associated with patient survival." (PMID 36737799, 2023). "However, epithelial mesenchymal transition (EMT) characteristic of basal tumors causes resistance to EGFR inhibitors in bladder carcinoma cells." (PMID 36737799, 2023). "Indeed, EGFR/HER2 protein overexpressions have been reported in some bladder cancer tissues and these are associated with more aggressive diseases." (PMID 35928267, 2022). "In a large-scale multi-omics analysis, elevated expression of PKCα protein was associated with poor prognosis in patients with bladder cancer, in addition to increased expression of beclin, epidermal growth factor receptor (EGFR), annexin-1, and AXL proteins and downregulation of Src protein." (PMID 36358843, 2022). "EGFR positivity is also associated with bladder cancer progression." (PMID 36471329, 2022). "We have previously reported the identification of the shed ectodomains of HAI-1, EpCAM and EGFR in the urine of bladder cancer patients; elevated urine levels of the shed ectodomains of EpCAM and EGFR are associated with worse bladder cancer (BC) specific survival." (PMID 29861867, 2018). "Moreover, the expression level of EGFR is highly associated with tumor grade, stage progression, and poor therapeutic outcome in bladder cancer, as reported in numerous studies." (PMID 29701711, 2018). "EGFR mutation has been identified as the most commonly-mutated gene in bladder cancer patients." (PMID 28165387, 2017). "However, mutations within the kinase domain and truncations of the EGFR are rarely seen in bladder cancer, and they have emerged as attractive therapeutic targets." (PMID 27091477, 2016). "Attenuation of the epithelial-to-mesenchymal transition (EMT) and inhibition of EGFR/p-AKT signaling may be the mechanisms underlying the tumor-suppressive role of miR-424 in bladder cancer." (PMID 26090723, 2015).
bladder cancer (continued). "Connecting AR in prostate and bladder cancers, dysregulation of the epidermal growth factor receptor (EGFR) is associated with bladder cancer, suggesting that these cancer pathways may be interconnected." (PMID 26347776, 2015). "A decreased rate of cell proliferation might indeed explain the less aggressive phenotypes frequently observed in FGFR3-mutated bladder carcinomas, in comparison with EGFR over-expression cases." (PMID 24250280, 2013). "In most studies, the high EGFR expression was associated with worse clinicopathologic prognostic parameters, as it was observed in the head and neck tumors, breast, lung and bladder cancer." (PMID 22475688, 2012). "Thus, a novel signaling axis, involving MD and its associated proteins Src/EGFR/c-Met, has been identified as an anti-apoptotic mechanism that seems to be peculiar to bladder carcinoma cells." (PMID 22988500, 2012). "Furthermore, up-regulation of EGFR/ErbB family receptors is associated with increasing grade and stages of bladder cancer." (PMID 23226356, 2012). "Another oncogene implicated in bladder cancer, namely epidermal growth factor receptor (EGFR)." (PMID 19243595, 2009). "In osteosarcoma (OS), ciR‐ITCH exerts oncogenic effects by activating the miR‐7/EGFR pathway, whereas in bladder cancer, it acts as a tumor suppressor through the miR‐17/miR‐224/p21/PTEN axis." (PMID 41541658, 2026). "Inhibition of EGFR has been shown to suppress tumor growth and improve outcomes in preclinical bladder cancer models." (PMID 41256326, 2025). "METTL1 can affect the m7G tRNA-mediated codon-specific translation of EGFR/EFEMP1 by regulating tRNA m7G modification to regulate bladder cancer cell behavior." (PMID 40360483, 2025). "Particularly, METTL1 acts as an oncogenic factor in bladder cancer via m 7G modifying certain tRNAs and regulating the expression of epidermal growth factor receptor (EGFR) and EFEMP1." (PMID 40483535, 2025). "Among these, two (EGFR and THBS1) were associated with bladder cancer based on Kyoto Encyclopedia of Genes and Genomes (KEGG) pathway enrichment analysis." (PMID 40833781, 2025). "Epidermal growth factor receptor (EGFR) is overexpressed in bladder cancer with a positive correlation between levels of EGFR, progression, and prognosis." (PMID 39858014, 2025). "Elevated EREG expression activates epidermal growth factor receptor (EGFR) signaling pathways that promote cell proliferation in bladder cancer." (PMID 38673992, 2024). "In Yan’s study, FAT10 was shown to activate AKT signaling by stabilizing EGFR in bladder cancer cells." (PMID 38514854, 2024). "For example, one research suggested that patients with bladder cancer, who transmitted EGFR overexpression, had poor response toward chemotherapy, indicating the importance of new treatments." (PMID 39678505, 2024). "These versatile nanoparticles demonstrated enhanced uptake into epidermal growth factor receptor (EGFR)-overexpressing T24 bladder cancer cells via receptor-mediated cellular internalization." (PMID 39120308, 2024). "TaqMan arrays can be used to find mutations in genes, like the EGFR and KRAS genes, that are commonly changed in bladder cancer cases." (PMID 39678505, 2024). "The expression of FAM83A, considered a potential biomarker in lung and bladder cancers as well as contributed to EGFR‐TKI resistance, was activated in SKBR3_HR cells, accompanied by a significant loss of H3K27me3 but stable H3K4me3 signals at promoter regions." (PMID 38460162, 2024). "In our study, hyperoside activated the EGFR-Ras signaling and induced the phosphorylation of Akt at Ser473 in T24 bladder cancer cells, thereby promoting cell proliferation and preventing cell apoptosis." (PMID 38464829, 2024). "EGFR gene expression, for instance, which tends to be overexpressed in bladder cancer, is one such biomarker." (PMID 39678505, 2024).
bladder cancer (continued). "KEGG analysis identified a total of 147 pathways, mainly AGE-RAGE signaling pathway in radial composites, bladder cancer, EGFR tyrosine kinase inhibitor resistance, pathways in cancer, and HIF-1 signaling pathway." (PMID 39312335, 2024). "Our laboratory demonstrated that arsenite-transformed malignant UROtsa cells exhibit characteristics of the basal muscle-invasive phenotype of bladder cancer, including high expression of basal markers such as EGFR, KRT1, KRT5, and KRT6." (PMID 38539513, 2024). "Vascular ECs can interact with bladder cancer cells and tissues to promote cancer progression by activating the epidermal growth factor receptor (EGFR) signaling pathway." (PMID 38542078, 2024). "In particular, EGFR, which is overexpressed in more than 70% of human bladder cancer, is also observed in the canine patient population." (PMID 37009802, 2023). "Previous studies have reported the co-expression of LAMC2 and EGFR in various cancers including cholangiocarcinoma, anaplastic thyroid carcinoma, and bladder cancer." (PMID 37542131, 2023). "Exosomal EDIL-3 was one of the proteins that activated epidermal growth factor receptor signaling, inducing bladder cancer cell migration." (PMID 37805491, 2023). "Overall, the obtained results indicate that the THE NPs can target the EGFR and inhibit its signaling and downstream pathways in the model of bladder cancer." (PMID 37933289, 2023). "Co-expression of LAMC2 and EGFR have also been reported in bladder cancer, anaplastic thyroid carcinoma, and cholangiocarcinoma." (PMID 37542131, 2023). "Several genes including epidermal growth factor receptor (EGFR)/ERK signaling were upregulated in bladder cancer." (PMID 37920327, 2023). "Inhibition of EGFR expression by JorA would be beneficial to improve the survival of patients with bladder cancer." (PMID 37587470, 2023). "For example, the SE-driven oncogenes SOX4 and EGFR participate in cell migration and invasion in bladder cancer." (PMID 37501079, 2023). "The basal cell cancers, which represent roughly 20%–25% of bladder cancers, appear to be responsive to EGFR inhibitors." (PMID 37169023, 2023). "For example, the interaction between ECs and cancer cells enhances EC recruitment and promotes cancer progression through the EGFR-NF-kB-CXCL5-CXCR2 pathway in bladder cancer." (PMID 36980564, 2023). "Bladder cancer in both species shares molecular targets such as EGFR, HER2, CDKN2A, CDKN2B, PIK3CA, BRCA2, and NF-κB16,69." (PMID 37009802, 2023). "EGFR TKIs enhance the radioactivity of bladder cancer cells by synergistically blocking EGFR and HER2." (PMID 36642742, 2023). "EGFR signaling pathway was identified as a potential therapeutic target significantly dysregulated in bladder cancer especially basal type." (PMID 36737799, 2023). "Depletion of RNF126 remarkably impaired proliferation and metastasis of bladder cancer cells via modulation of the EGFR/PI3K/AKT pathway." (PMID 37215134, 2023). "Proguanil, which is often used as an anti-malarial drug, inhibited the cell growth by promotion of EGFR degradation and induction of autophagy in bladder cancer." (PMID 37215134, 2023). "Bladder cancer was proved to have differential enrichment of cell surface proteins, including EGFR and HER2, according to the molecular subtype." (PMID 36737799, 2023). "Cetuximab enhanced the therapeutic effect in bladder cancer cells by affecting the EGFR signals via both ADCC and CDC-based mechanisms." (PMID 36575233, 2022).